RN7SL198P (RNA, 7SL, cytoplasmic 198, pseudogene)
Gene: Miscellaneous RNA gene on chromosome 10 (12,328,132 to 12,328,389, reverse strand). Ensembl gene ENSG00000264036.
Homologues: Orthologues: chimpanzee Metazoa_SRP (99% identical), macaque Metazoa_SRP (53% identical). Paralogues in human: RN7SL774P (66% identical), RN7SL96P (66% identical), RN7SL596P (65% identical), RN7SL353P (65% identical), RN7SL491P (64% identical), RN7SL376P (64% identical), RN7SL391P (64% identical), Metazoa_SRP (63% identical), RN7SL274P (63% identical), RN7SL470P (62% identical), RN7SL847P (62% identical), Metazoa_SRP (62% identical), and 698 more.